IL6 (interleukin 6)
Diseases named in the same sentence as IL6 in open-access papers (continued):
Sharing a sentence is not in itself a finding about the gene and the disease.
pancreatic cancer (460 papers, 2003 to 2026). "Remarkably, pancreatic cancer patients experiencing weight loss showed significantly increased serum levels of IL-6 and TNF-α compared to those whose weight remained stable." (PMID 40869331, 2025). "By binding to CXCR4/CXCR7 on the SCs, SCs downregulate the expression of multiple pain associated targets to attenuate pain perception, while IL-6 secreted by activated SCs suppresses pain signaling, collectively delaying pancreatic cancer diagnosis." (PMID 40248695, 2025). "Interleukin 6 (IL-6) is another interleukin involved in inflammation, cell proliferation and differentiation, and its gene polymorphisms are associated with pancreatic cancer." (PMID 39195299, 2024). "Clinical data statistics indicate that progressive weight loss, fatigue, and other cachexia symptoms in patients with advanced pancreatic cancer are often positively associated with serum IL-6 levels." (PMID 38828409, 2024). "Previous reports indicate that systemic inflammation and elevated IL-6 levels are associated with an unfavorable prognosis in patients with pancreatic cancer." (PMID 38672257, 2024). "Elevated levels of inflammatory-mediated cytokines such as IL-6 and IL-10 have been associated with poor prognosis in patients with pancreatic cancer." (PMID 38662232, 2024). "The protein interacts with CA125 and has been linked to Akt-induced IL-6 production associated with enhanced mitochondrial respiration in pancreatic cancer." (PMID 38396817, 2024). "Serum levels of IL-6, IL-8, IL-10, and IL-1RA were significantly increased in pancreatic cancer patients and were associated with worse survival rates, poor performance status." (PMID 36899319, 2023). "MyD88 hyperactivation causes NFkB activation and IL-6 secretion in CAFs, and IL-6 further triggers STAT3 signaling activation in pancreatic cancer." (PMID 38933287, 2023). "This study aimed to enhance antitumor immune responses to pancreatic cancer via Ab-based blockade of IL-6 and cytotoxic T-lymphocyte–associated protein 4 (CTLA-4)." (PMID 36881480, 2023). "Il-6 is known to be increased in cancer cachexia and to correlate with weight loss in pancreatic cancer patients, and anti-IL-6 drugs are able to diminish muscle loss in preclinical models." (PMID 36980729, 2023). "Elevated levels of IL-6 and IL-10 in the serum of pancreatic cancer patients have been associated with a poor prognosis." (PMID 37760608, 2023). "Both pancreatic cancer cells and CAFs produce IL-6, which causes increased tumor cell migration and invasion, as well as epithelial to mesenchymal transition (EMT)." (PMID 35493517, 2022). "In pancreatic cancer, elevated serum IL-6 and IL-10 concentrations have been linked with worse prognosis, as has the pro-inflammatory cytokine IL-18." (PMID 35034144, 2022). "In patients with pancreatic cancer, a high level of serum IL-6 is associated with cachexia, resulting in promoted niche formation in pancreatic cancer liver metastasis and a poor prognosis." (PMID 35493517, 2022). "Numerous previous studies reported that inflammatory biomarkers, including C-reactive protein (CRP) and interleukin-6 (IL-6), were independently associated with overall survival in (from only 7 to 474) patients with pancreatic cancer." (PMID 34572824, 2021). "Bazedoxifene has been investigated in vitro in combination with anti-interleukin 8 (IL-8), that is overexpressed in pancreatic cancer tissues and blood circulation, and is associated to metastasis and poor prognosis as well as IL-6." (PMID 34451837, 2021). "Low-fat diet and physical activity are associated with significant reduction of white adipose tissue low-grade inflammation, IL-6 release and macrophage infiltration, as well as decrease of pancreatic cancer risk." (PMID 32659999, 2020). "Interleukin-6 (IL-6), a major mediator of inflammation, is reported to be a diagnostic biomarker or a prognostic indicator of survival in patients with pancreatic cancer." (PMID 32758252, 2020).
pancreatic cancer (continued). "Clinical trials have shown an association between circulating IL6 and degree of both weight loss and survival rates in pancreatic cancers." (PMID 31323984, 2019). "IL-6, a prominent cachexia-associated factor in pancreatic cancer, which was remarkably increased in the serum of Pan02 tumor-bearing mice, whereas that of the tumor naive mice was below the detection limit." (PMID 31073508, 2019). "It is well known that elevated levels of IL-6 are associated with increased cachexia and decreased survival in pancreatic cancer patients." (PMID 31073508, 2019). "Subsequently, it inhibits STAT3 phosphorylation and transcription induced by IL6, causing apoptosis, blocking cell migration in pancreatic cancer cells and suppressing tumor growth." (PMID 31139333, 2019). "Inflammation within the pancreatic tumor environment has been linked to chemo-resistance and tumor progression through NFκB, IL6 (interleukin 6), Toll like receptor and TGFβ pathways." (PMID 30582059, 2018). "For pancreatic cancer, the results of the studies assessed were unanimous showing a significant association between high circulating IL-6 and short OS, which was confirmed in the meta-analysis." (PMID 30038723, 2018). "Three studies assessed the use of IL-6 as a diagnostic biomarker in patients with pancreatic cancer, all finding IL-6 useful." (PMID 30038723, 2018). "Nevertheless, genetic knockdown or pharmacological inhibition of ILK caused depleted MUC1-C expression in IL-6-treated pancreatic cancer cells, indicating that ILK is required to sustain STAT3-induced MUC1 upregulation by maintaining its stability." (PMID 28692035, 2017). "Identification of high risk factors contributing to increased serum IL-6 levels in chemo-naïve advanced pancreatic cancer patients." (PMID 28177923, 2017). "In particular, IL-6 has emerged as an important factor in the modulation of cancer-associated inflammation, and pancreatic cancer cells highly express this cytokine." (PMID 29245934, 2017). "Our model of pancreatic cancer cachexia was associated with marked elevations in serum levels of IL-6." (PMID 26172047, 2015). "Elevated cytokine levels, including IL-6 and IL-10, have been associated with poor performance, weight loss, and decreased survival in pancreatic cancer patients." (PMID 24624094, 2014). "Circulating levels of IL-6 correlate with weight loss and reduced survival in pancreatic cancer patients." (PMID 24624094, 2014). "Accumulating evidence suggests that IL-6 is frequently elevated and thus is associated with a poor prognosis in many types of cancer, including pancreatic cancer." (PMID 23922983, 2013). "In conclusion, SOCS-1 is commonly methylated in pancreatic adenocarcinoma and loss of SOCS-1 in pancreatic cancer is moderately associated with increased IL-6-mediated growth." (PMID 12865927, 2003). "Furthermore, a study has shown that lorazepam, a specific type of BZRA, induces IL‐6 expression in cancer‐associated fibroblasts via G protein‐coupled receptor 68, which is associated with reduced survival of patients with pancreatic cancer." (PMID 40368363, 2025). "Interestingly, IL-6 has been identified as an inflammatory marker associating with increased one-year mortality in pancreatic cancer patients." (PMID 38664691, 2024). "In addition, hepatocyte growth factor (HGF), fibrinogen, and inflammatory markers such as C-reactive protein (CRP) and interleukin-6 (IL6) have been linked to pancreatic cancer instances." (PMID 39200847, 2024). "Furthermore, IL-6 can cause synergistic amplification with other cytokines to facilitate progression of pancreatic cancer." (PMID 37415745, 2023). "Moreover, IL‐6 and IL‐8 play a major role in the inflammation of pancreatic cancer, and these two cytokines in the circulation are positively associated with pancreatic cancer progression and predicted poor prognosis." (PMID 35871313, 2023).
pancreatic cancer (continued). "A number of circulating pro-inflammatory cytokines have been implicated in pancreatic cancer cachexia including interleukin 6 (IL-6), interleukin 8 (IL-8), transforming growth factor beta (TGF-β), tumor necrosis factor alpha (TNFα), and monocyte chemoattractant protein-1 (MCP-1)." (PMID 30513792, 2018). "Interleukin-6 (IL-6), a vital inflammation-related cytokine that is enhanced by hypoxia and K-ras, and in turn contributes to the formation of the tumor microenvironment, has been implicated in pancreatic cancer angiogenesis and metastasis." (PMID 26894969, 2016). "In summary, intracellular ANXA2 can directly regulate the transcriptional activity of NF-κB by binding to the p50 subunit of NF-κB, inducing gemcitabine resistance in pancreatic cancer cells through upregulation of anti-apoptotic genes, including that encoding IL-6." (PMID 25611381, 2015). "Levels of IL-6, IL-8, IL-10, and IL-23 were significantly associated with the direct number of circulating bone marrow (BM)-derived mesenchymal or very small embryonic/epiblast-like stem cells (SCs) in patients with pancreatic cancer." (PMID 24849506, 2014). "We tested the hypothesis that high plasma YKL-40 and IL-6 associate with pancreatic cancer and short overall survival." (PMID 23840582, 2013). "Moreover, and uniquely in pancreatic cancer studies, research indicated that lower IL-6 might associate with a better disease outcome, where IL-6 clearly acts as a pro-inflammatory biomarker for this cancer type." (PMID 37181043, 2023). "Previous studies have stated that elevated MDSC levels were associated with reduced overall survival in patients with pancreatic cancer, and IL-6 produced by PSCs in TME could activate MDSC via JAK/STAT3 (Janus kinase/signal transducer and activator of transcription 3) signaling." (PMID 29254283, 2017). "Interestingly, increased cytokine levels are thought to be poor prognostic factors in cachexia, as studies have shown that IL-6 polymorphisms and elevated levels of IL-6 are associated with increased cachexia and decreased survival in pancreatic cancer patients." (PMID 26172047, 2015). "After measuring cytokine levels (IL-6, IL-8, IL-10, IL-23, TNFα) in this group, we added these patients to our analyses, constructed ROC curves, and determined the approximate AUC values to assess the suitability of these cytokines as diagnostic markers for pancreatic cancer." (PMID 24849506, 2014). "Currently, a Phase II clinical trial is evaluating the IL‐6 antibody (tocilizumab) combined with chemotherapy for pancreatic cancer, aiming to improve treatment response and alleviate cachexia." (PMID 41583906, 2026). "The ability of ALP to regulate proinflammatory cytokine production is maintained in vivo as ALP-treated mice bearing pancreatic tumors exhibited reductions in IL6 within the tumor interstitial fluid." (PMID 41996628, 2026). "Preclinical studies demonstrate that blocking IL‐6 combined with immune checkpoint inhibitors significantly suppresses pancreatic tumor growth." (PMID 41583906, 2026). "In pancreatic cancer, iCAFs also show high Lamin A/C and pro-inflammatory cytokines such as IL-6, IL-8, CXCL1, and CXCL12." (PMID 40846900, 2025). "The anti-inflammatory effects of exercise are particularly relevant in GI cancers such as pancreatic cancer, where IL-6-driven cachexia is often severe." (PMID 40869331, 2025). "Here, we investigated the role of IL-6 in TGFβ-specific immunity in a murine model of pancreatic cancer." (PMID 39653766, 2025). "Numerous investigations have underscored the connection between increased IL-6 expression and a worse prognosis, as well as chemotherapy resistance, in patients with pancreatic cancer, non-small cell lung cancer (NSCLC), ovarian cancer, and other malignancies." (PMID 40433391, 2025). "Thereby, following MCPIP1 overexpression and knockdown, we then examined changes in the IL6/JAK/STAT3 axis in pancreatic tumor cells." (PMID 40874680, 2025).
pancreatic cancer (continued). "Combined blockade of IL-6 and PD-L1 inhibits pancreatic cancer progression and prolongs survival by increasing the infiltration of intratumoral effector CD8+ T cells and promoting the conversion of circulating CD4+ T cells to the Th1 phenotype." (PMID 40948749, 2025). "For example, in pancreatic cancer, IL-6 blockade resulted in increased effector T cell infiltration and enhanced efficacy of anti–PD-L1 therapy." (PMID 40762981, 2025). "Pancreatic tumors secrete pro-inflammatory cytokines such as IL-6 and TNF-α, which promote muscle protein degradation through the ubiquitin–proteasome pathway." (PMID 40002202, 2025). "Preclinical studies have shown that blocking IL-6 receptor enhances the therapeutic effect of programmed cell death ligand 1 (PD-L1) and inhibiting IL-6 expression exhibited promise in suppressing pancreatic cancer progression." (PMID 40248695, 2025). "IL-6 is one proinflammatory cytokine which induces skeletal muscle wasting in multiple models of cancer cachexia, including pancreatic cancer." (PMID 40655023, 2025). "The expression of the proto-oncogene Kras in the pancreas activates the Stat3/Socs3 signaling pathway, which relies on IL-6 and its downstream signaling pathways, ultimately promoting pancreatic cancer development." (PMID 39981173, 2025). "For instance, KRAS overactivation in pancreatic cancer increases interleukin-6 (IL-6) secretion, which facilitates tumour development via the JAK1/STAT3 pathway and triggers reactive oxygen species generation and oxidative stress responses." (PMID 39820726, 2025). "The cytokines interleukin-6 (IL-6) and interleukin-23 (IL-23) increase AR expression in prostate and pancreatic cancers." (PMID 40935826, 2025). "Recent studies have shown that ZIP4 upregulation in pancreatic cancer promotes the IL-6/STAT3 signalling pathway and activates the production of neuropilin-1 and vascular endothelial growth factor (VEGF), thereby enhancing tumour growth and angiogenesis." (PMID 40869403, 2025). "Correlations between high levels of circulating IL-6 and poor survival have been observed in various cancers, including pancreatic cancer." (PMID 39653766, 2025). "Recent studies in pancreatic cancer further emphasize the central role of IL-6, showing that an IL-6 trans-signaling loop between the tumor, fat, and muscle drives progressive wasting in this model." (PMID 40869331, 2025). "In the immune evasion process of pancreatic cancer cells, inflammatory factors like IL-6, TNFα, and IL-10 have been found to be significantly involved." (PMID 40487760, 2025). "We also addressed the importance of IL-6 for TGFβ-specific immunity in patients with pancreatic cancer." (PMID 39653766, 2025). "Antibodies blocking IL-6 combined with PD-1 were proved to strikingly elevate survival rate of mice with pancreatic cancer." (PMID 40248695, 2025). "In pancreatic cancer, high PCDH17 expression associates with elevated inflammatory factors (TGF-β, IL6-JAK-STAT3, TNFA pathways) and enhanced immune activity, including antigen presentation and T-cell recruitment." (PMID 40487760, 2025). "IL6 levels were examined in the 12 pancreatic cancer patients from the P001 study, with OT-101 treatment at 140 mg/m2/day." (PMID 40650134, 2025). "These inflammatory factors, such as TNF-α and IL-6, can upregulate the expression of matrix metalloproteinases (MMPs), degrading the extracellular matrix and promoting the invasion and metastasis of pancreatic cancer cells." (PMID 40430234, 2025). "In pancreatic cancer, IL-6 plays a crucial role from the early stages of pancreatic intraepithelial neoplasia (PanIN) to the metastasis of pancreatic cancer cells." (PMID 39125732, 2024). "In pancreatic cancer, pancreatic stellate cells release significant quantities of IL-6, which signals downstream activation of AMPK." (PMID 38828409, 2024).
pancreatic cancer (continued). "Stellate cells in the TME of pancreatic cancer also secrete IL-6 and drive the activation of the JAK2-STAT3 pathway, which leads to the accumulation of myeloid-derived suppressor cells and the maintenance of an immunosuppressive microenvironment." (PMID 38273295, 2024). "IL-6 is a key biomarker for the diagnosis and prognosis of pancreatic cancer and a potential target for therapeutic interventions." (PMID 39125732, 2024). "Researchers have found that a cytokine called Interleukin-6 (IL-6) is involved in the entire course of pancreatic cancer, promoting its occurrence and development." (PMID 38828409, 2024). "By analyzing the published single‐cell sequencing data of PDAC,31, 32, 33 we observed significantly lower IL‐6 expression in pancreatic cancer tissues compared to normal pancreatic tissues." (PMID 39235042, 2024). "In this paper, we aim to comprehensively expound upon the mechanisms through which IL-6 contributes to the onset and progression of pancreatic cancer, while also highlighting potential directions for clinical treatment of the disease." (PMID 38828409, 2024). "Martinoni and colleagues conducted immunohistochemical staining on tissue sections from pancreatic cancer patients, they found that IL-6 exhibited greater immunoreactivity in tissue regions of patients with cachexia compared to those without cachexia." (PMID 38828409, 2024). "The reported mechanisms by which PSCs and CAFs interact with and induce chemoresistance in pancreatic cancer cells involve the Notch, mTOR, and IL-6/JAK/STAT3 pathways." (PMID 38318525, 2024). "Considering these promising findings, there is strong rationale to believe that IL-6 antibodies hold significant potential in combination therapies for pancreatic cancer." (PMID 38828409, 2024). "The IL-6 signaling pathway is a key factor in the development of pancreatic cancer, with the IL-6/JAK/STAT pathway playing a particularly crucial role." (PMID 38828409, 2024). "It has been demonstrated that IL-6 is overexpressed in pancreatic tissue and that pancreatic cancer patients with cachexia have higher serum levels than patients without it." (PMID 38539528, 2024). "In recent years, cachexia has been found to be intricately linked to the host itself and numerous tumor-derived cytokines, with IL-6 being identified as one of the factors related to cachexia in pancreatic cancer." (PMID 38828409, 2024). "Their findings suggest that IL-6 can stimulate pancreatic cancer cells to release Th2 cytokines, consequently fostering the generation of Th2 cells and indirectly facilitating immune evasion by tumor cells." (PMID 38828409, 2024). "In a mouse model of pancreatic cancer, the injection of recombinant IL-6 not only elevated corticosterone levels but also led to the depletion of immune cells such as CD4+T cells, CD8+T cells, and NK cells." (PMID 38828409, 2024). "IL-6 and Kras genes collaborate to advance the progression of PanIN to pancreatic cancer, with the signals they generate playing a crucial role in tumor growth." (PMID 38828409, 2024). "Although overexpression of TIM‐4 leading to an increased proportion of Tregs was also observed in an in‐situ model of mouse pancreatic cancer, we cannot attribute the phenomenon in vivo solely to decreased IL‐6 secretion at present." (PMID 39235042, 2024). "Given that IL-6 adversely impacts the prognosis in patients with pancreatic cancer, blocking the IL-6 signaling pathway has been proposed as a potentially effective strategy for those with advanced PDAC." (PMID 38672257, 2024). "On the other hand, WDR5 depletion leads to the effective downregulation of immune checkpoints and immunosuppressive cytokines, including TGFβ and IL6, in the pancreatic tumor microenvironments." (PMID 39201460, 2024). "While IL-6 targeted drugs are currently utilized in pancreatic cancer treatment, the effectiveness of individual drugs seems to be limited, likely due to variations among individuals and small sample sizes." (PMID 38828409, 2024).